ITGB1 (integrin subunit beta 1)
Diseases named in the same sentence as ITGB1 in open-access papers (continued):
Sharing a sentence is not in itself a finding about the gene and the disease.
tumor (continued). "Several studies have shown that ITGB1 is widely overexpressed in tumours such as the lung, breast, and colorectal tumours and plays an important role in their survival and metastatic potential 15-20." (PMID 33613118, 2021). "ITGB1 is an integrin, mainly expressed in normal cells and tumor-related cells, regulating angiogenesis, tumor progression, apoptosis and metastasis." (PMID 33345684, 2021). "β1 integrin (ITGB1) is the integrin protein mainly expressed in normal cells and tumor-related cells." (PMID 33345684, 2021). "In this experiment, the colony growth of tumor cells was significantly inhibited, and elevated cell apoptosis was observed in ITGB1 KO SGC-7901/BGC-823 cells." (PMID 34758833, 2021). "Other studies revealed that ITGB1 mediates tumour resistance to diverse anti-cancer drugs including erlotinib, bevacizumab, gemcitabine, and gefitinib 21-24." (PMID 33613118, 2021). "Results indicated that the methylation level of ITGB1 was decreased in 60% of HCC tumor tissues in contrast with tumor-adjacent normal tissues." (PMID 34977001, 2021). "Affects the binding of ITGB1 to Collagen I and tumor cell motility to promote the bone metastasis of PCa." (PMID 34124065, 2021). "Interrogation of an NSCLC dataset (1,102 cases including 103 normal tissues and 999 tumour tissues) from TCGA revealed that ITGB1 is overexpressed in NSCLC." (PMID 33613118, 2021). "It is also reported that ITGB1 can decrease the adhesiveness between tumor cells, promote the detachment of tumor cells from the tumor body, and enhance adhesion between tumor cells and the ECM." (PMID 33014056, 2020). "In vivo experiments showed that ITGB1 downregulation can inhibit tumor growth and peritoneal metastasis." (PMID 33335550, 2020). "METTL3 regulates the expression of Integrin β1 (ITGB1) through m6A-HuR-dependent mechanism, which affects the binding of ITGB1 to Collagen I and tumor cell motility, so as to promote the bone metastasis of PCa." (PMID 33015074, 2020). "We observed the ITGA1/A2/A4/A5/A7/A8/A11/A2B/AL/ AM/AV/AX and ITGB1/B2/B3/B5/B6/B7 showed significantly obvious correlation with tumor purity in OC." (PMID 32765584, 2020). "Taken together, tumor-suppressive miRNAs controls the expression of ITGA2/ITGB1 and ITGA3/ITGB1 in PDAC cells, and the aberrant expressions of these integrins can play pivotal roles in the malignant features of PDAC." (PMID 32899691, 2020). "The deposition of COL4A1 protein can activate the ITGB1 signaling pathway in tumor tissues, and then the elasticity and adhesion ability of cancer cells are reduced." (PMID 32637572, 2020). "ITGB1 is mainly related to the ability of tumor metastasis to promote primary tumor exosmosis, cell adhesion, intravenous injection and tumor growth at metastatic sites." (PMID 33101383, 2020). "ITGA1 dimerizes with ITGB1 to bind collagens I, IV, VI, and fibrillar collagens, making it an excellent candidate to affect tumor cell adhesion to the peritoneum." (PMID 32525899, 2020). "We showed that a combination of PODXL with ITGB1 and a combination of BCL7B with ITGB1 predicted the postoperative outcomes of PDAC patients better than tumor size and the TNM staging system." (PMID 31166991, 2019). "Univariate Cox regression analysis revealed that UICC TNM stage, high ITGB1 expression, tumor size, and venous invasion served as independent prognostic factors." (PMID 31166991, 2019). "In LADC, the altered tumor microenvironment caused by hydrogen peroxide can potentially cause the dysregulation of EGFR, EpoR, and ITGB1 (CD29) signaling pathways." (PMID 31217907, 2019). "In conclusion, the combination of PODXL with ITGB1 and the combination of BCL7B with ITGB1 accurately predicted the postoperative prognosis of PDAC patients better than tumor size and the UICC TNM stage." (PMID 31166991, 2019). "In LSCC, a hypoxic tumor microenvironment exposed to xenobiotic toxicity nicotine can potentially cause the dysregulation of IGF-1R, ITGB1 and TNS1 signaling pathways." (PMID 31217907, 2019).
tumor (continued). "In the present study, we investigated the use of PODXL, BCL7B, ARHGEF4, and ITGB1 as useful markers for the prognosis of postoperative PDAC patients in comparison with tumor size and the TNM staging system." (PMID 31166991, 2019). "Our present data showed that both ITGA3 and ITGB1 were directly regulated by anti-tumor miR-124-3p in PDAC cells, and knockdown of these genes or ectopic expression of miR-124-3p significantly blocked cancer cell aggressiveness." (PMID 29988949, 2018). "ITGB1 forms a heterodimeric complex with various integrin subunits and regulates cell focal adhesion and tumor metastasis." (PMID 28423650, 2017). "These genes are known to be implicated in proliferation (MAPK8), metastatic diffusion of tumor cells (ITGB1), drug resistance (ANXA1), coagulation (ANXA3, ANXA5) or inflammation (HPGD, NFKB1)." (PMID 29228619, 2017). "Integrin β1 (ITGB1), a known EV protein, is important for invadopodia formation and ITGB1 gene levels are elevated in GBM tumours." (PMID 27770278, 2017). "In the present study, we reported that hTERT can decrease miRNA-29a levels to indirectly enhance ITGB1 expression, which triggers tumor metastasis." (PMID 26903137, 2016). "Many studies have indicated that ITGB1 is abnormally expressed in a variety of tumor types and that a high expression level of ITGB1 is closely associated with a poor prognosis of cancer patients." (PMID 26903137, 2016). "This included EC-specific proteins (e.g. COL1A1, FBN1), tumour-specific proteins (e.g. ITGB1) and proteins up-regulated in both cell types (FN1, THSB1, CD44, ITGA4, CTGF)." (PMID 27049916, 2016). "ITGB1 is often expressed abnormally in cancer and correlates with malignant tumor phenotypes, such as invasion, migration, angiogenesis and proliferation." (PMID 26903137, 2016). "Recent research in lung cancer has established that RBP2 is correlated to tumor migration and invasion by directly binding to integrin β1 (ITGB1) promoters." (PMID 25162518, 2014). "In another work, we found that integrin β1 (ITGB1) was significantly overexpressed on CAFs and was responsible for forming the dense tumor stroma, and a specific peptide (FNIII14) derived from fibronectin was demonstrated to act on ITGB1 to induce the inactivation of CAFs." (PMID 41355964, 2026). "This suggested that the ligand-receptor interactions between THBS2 and ITGB1 might play a regulatory role in spatial communication between tumor cells and other cell types." (PMID 40688093, 2025). "The mRNA and protein levels of ITGB1 are significantly upregulated in a variety of tumor tissues." (PMID 40821990, 2025). "We identified CD36, MMP1, TGFBR3, TWIST2, ITGB1, and FGF19 as associated with poorer outcomes: CD36 enhances tumour stemness and growth, MMP1 facilitates metastasis, TGFBR3 and TWIST2 promote EMT and invasion, ITGB1 supports cell adhesion and survival, and FGF19 drives proliferation." (PMID 41007296, 2025). "Notably, several ligand-receptor pairs associated with tumor progression were identified between fibroblasts and immune cells, including FN1-(ITGA8+ITGB1), FN1-CD44, COL4A2-CD44, and ANGPTL1-(ITGA8+ITGB1)." (PMID 40963856, 2025). "Notably, the Piezo1/ITGB1 axis was predominantly localized in CAFs and epithelial cells, suggesting a key role in establishing the relationship between the tumor and the ECM." (PMID 40667648, 2025). "However, high intratumoral ITGB1–WFL was associated with high T class, making it an attractive biomarker candidate for tumor invasiveness." (PMID 40287842, 2025). "ITGB1 regulates tumor cell resistance through downstream signaling pathways." (PMID 40685383, 2025). "By interfering with ALKBH5 expression, this study further explored its role in OC, revealing that ALKBH5 may regulate ITGB1 m6A modification, thereby affecting tumor cell proliferation and apoptosis." (PMID 40585991, 2025). "Moreover, the integrin complex ITGA6+ITGB1 has been correlated with tumor cell adhesion, invasion, and migration." (PMID 39944338, 2025).
tumor (continued). "Subsequently, we determine whether the tumor cells-secreted SPP1 could influence CD8+T cells function by regulating ITGA4/ITGB1 expression." (PMID 40665335, 2025). "In addition to FN1, high risk of tumor recurrence was associated with higher expression of ITGAV, ITGB1 and ITGB6." (PMID 40423510, 2025). "Similarly, ITGB1, a cell surface receptor involved in cell adhesion and migration, plays a pivotal role in tumor progression." (PMID 40817072, 2025). "Therefore, we examined the extent of fibrosis in heart sections derived from control MDX mice compared with PyMT ITGB1 KO-tumor-bearing mice and MEFI- and MEFP-injected mice by Masson’s Trichrome staining." (PMID 38673859, 2024). "A recent study found paracrine and autocrine COL8A1 could bind to ITGB1 promoting tumor progression and gemcitabine resistance in PAAD." (PMID 39732719, 2024). "Numerous studies have demonstrated that ITGB1, an integrin that belongs to the 1 subgroup, regulates cell–matrix contact and is essential for sustaining tumor stemness, proliferation, dissemination, metastasis, radiotherapy, chemotherapy, and medication resistance." (PMID 38402311, 2024). "Finally, a multi-platform analysis revealed that three of the 33 malignancies had significantly altered ITGB1 expression in tumor tissues in comparison to normal tissues." (PMID 38402311, 2024). "Additionally, MDK-SDC2 and MDK-(ITGA4+ITGB1) signals from fibroblasts and tumor cells were only received by CPVLhi TAMs." (PMID 39776914, 2024). "ITGB1+ EVs are involved in ECM interactions and metastatic niche formation, while CD44+ EVs are linked to tumor recurrence and therapy resistance in GBM, suggesting their role as biomarkers for aggressive tumor subtypes." (PMID 39594703, 2024). "In glioma, FRK inhibits ITGB1 transcription, slowing tumor growth." (PMID 38279122, 2024). "Notably, we disclosed a significantly strong interaction between tumor cells with high ITGB1 expression (ITGB1high) and the macrophages." (PMID 39207055, 2024). "Notably, BCAN, VCAN, and JAM2 were predominantly expressed by tumor cells, while ITGB1 was ubiquitously expressed across all clusters." (PMID 39554845, 2024). "In this respect, we report that ITGB1-DDR interplay contributes to OR NSCLC tumour progression." (PMID 38177190, 2024). "Our preclinical data on this function of ITGB1 are strengthened by clinical data from a collection of matched primary tumor and liver metastasis samples from patients with SCLC that indicate a clear/significant increase of ITGB1 in liver metastasis in comparison with the primary tumor." (PMID 38775153, 2024). "We similarly observed a significantly slower tumor growth of the PyMT ITGB1 KO cells." (PMID 38673859, 2024). "In conclusion, our data suggest that high levels of ITGB1 and its overactivation may represent a biomarker of tumor invasion and progression after prolonged therapy with osimertinib and also with inhibitors of MAPK pathway like selumetinib." (PMID 38177190, 2024). "Additionally, we utilized the DSP method to perform transcriptome sequencing on 42 ROIs (each containing both tumor cells and macrophages) with high (n = 5) and low (n = 37) tumoral ITGB1 expression." (PMID 39207055, 2024). "Interestingly, stromal localization and the levels of active SMAD2 (SE = 2.1) and ITGA5/ITGB1 distinguish patient-protective from patient-detrimental desmoplasia and foretell tumor recurrences." (PMID 38892190, 2024). "To examine whether any RGD motif recognition integrins in LN229TAZ(4SA) cells could be involved, we knocked down ITGB1 or ITGA5 individually in the tumor cells through shRNAs targeting each of them (Fig. EV2D,E)." (PMID 38806658, 2024). "Furthermore, in vivo tumorigenic experiments uncovered that ITGB1 knockdown substantially repressed tumor growth and proliferation." (PMID 39207055, 2024).
tumor (continued). "Since ACBP expression controls FAO in GBM cells and here we show that FAO can subsequently modulate GBM tumor cell migration, we tested whether ITGB1 expression could be modulated directly by altering FAO." (PMID 37120445, 2023). "Additionally, IHC staining showed that ITGB1 prominently colocalized with β‐catenin in some areas of tumor specimens." (PMID 35864742, 2023). "In the FUSCC cohort, ITGB1 was expressed in the cytoplasm of tumor cells." (PMID 35864742, 2023). "In addition, PD-L1+ EVs expressed some tumor markers such as CD29 (integrin subunit beta 1) and stage-specific embryonic antigen-4 (SSEA-4)." (PMID 36980174, 2023). "Taken together, T/NK cells in PTC may form the immunosuppressive tumor microenvironment via FN1/ITGB1 interaction with other cells." (PMID 37733241, 2023). "Among these intergrins, ITGB1 promotes tumor metastasis and progression in various cancers 42,43." (PMID 36632222, 2023). "Notably, ITGB1 upregulation and signaling were detected in patients with leukemic CTCL and were associated with tumor cell trafficking, survival, proliferation, and resistance to apoptosis." (PMID 37669110, 2023). "In this study, we first established that PSO effectively inhibits OS cell proliferation, migration, and invasion in vitro and then demonstrated that it promotes OS cell apoptosis and inhibits OS tumor growth in vivo by downregulating ITGB1 expression via the FAK and PI3K/Akt signaling pathways." (PMID 37004120, 2023). "We suggest that upregulated ITGB1 in GC may promote immune suppression by elevating immunosuppressive cytokines in the tumor microenvironment." (PMID 35864742, 2023). "ITGB1 aggregation induced autophosphorylation of FAK at Tyr397, which triggered downstream Src kinase phosphorylation at Tyr416, initiating a variety of molecular signals associated with tumor progression." (PMID 36632222, 2023). "The relationship between ITGB1 and tumor immunosuppression in GC needs to be explored." (PMID 35864742, 2023). "Silencing the intracellular ITGB1 mRNA and protein expression reduced intracellular ITGB1 expression, which was associated with reduced HLEC tube formation, tumor cell migration, and invasion." (PMID 36632222, 2023). "Therefore, we assumed that the ITGB1/FAK axis is involved in tumor progression and distant metastasis in DTC." (PMID 37345058, 2023). "We found that the ITGB1-low group had significantly higher tumor non-silent mutation load, compared with the ITGB1-high group (Wilcoxon rank-sum test, P = 0.0089)." (PMID 37007126, 2023). "Here, we performed a comprehensive bioinformatics analysis of multiple datasets derived from CRC patients and showed that elevated expression of NID1 and the genes ITGA3, ITGB1, and ITGAV, which encode NID1 receptors, is associated with poor prognosis and advanced tumor stage." (PMID 38001576, 2023). "The tumor cell IHC scores of ITGB1 were between 0–18 (median = 7)." (PMID 35648752, 2022). "These indicated that targeting ITGB1 might eliminate the origin of tumor cells with cancer stem cell properties." (PMID 36186483, 2022). "Nevertheless, although further studies are needed to understand these discrepancies, the expression of ITGB1 and miR-183 and their association to disease status in our study and previous miRNA studies strongly favor a tumor suppressor for ITGB1 and oncogenic role for miR-183 in PrCa." (PMID 35202085, 2022). "Moreover, these patients exhibited significantly lower overall survival, when compared with those harbouring tumours with a low ITGB1/high CDH1 molecular phenotype." (PMID 34486077, 2022). "Furthermore, DCN, ITGB1, NOTCH3 and SPARC genes were discovered to be strongly associated not only with tumor response to nCRT but also with disease-free survival; they were further used to form a four-gene expression-based risk score." (PMID 35682714, 2022). "We then analyzed the expression of ITGB1 in tumor subtypes stratified from the TCGA-PAAD cohort." (PMID 35628269, 2022).
tumor (continued). "The mechanisms described via which ITGB1 induces tumor progression are diverse." (PMID 36456612, 2022). "The link between ITGB1 and Trop-2 mediated tumor progression could be of interest for the future as ITGB1 expression may be a potential biomarker of response prediction for SG therapy." (PMID 36456612, 2022). "In addition, the upregulated expression of ITGB1 was also significantly correlated with tumor metastasis and tumor necrosis." (PMID 36178365, 2022). "Thus, the available evidence of the direct targeting of ITGB1 by miR-183 was achieved in a scenario with the tumor suppressor miR-183 and oncogenic ITGB1." (PMID 35202085, 2022). "Normal AT2 cells demonstrated a significant decrease in gene expression of Itgb1 (integrin β1) in integrin β1–KO mice, while tumor cells from both cohorts demonstrated similar levels of integrin β1, suggesting that only AT2 cells that escaped integrin β1 deletion were able to develop into tumors." (PMID 35763345, 2022). "Science ITGB1 is a secretory protein; this molecule may be used as a circulating tumor marker for prognostic application." (PMID 34307149, 2021). "The tumor suppressive effects of ITGB1 knockdown were reversed by ITGB1 overexpression." (PMID 34758833, 2021). "It was also found that ITGB1 was an effective growth factor in a xenograft tumor mouse model." (PMID 33345684, 2021). "ITGB1 is an integrin family member and known as a membrane receptor involved in cell adhesion and recognition in a variety of processes including metastatic diffusion of tumor cells." (PMID 34638346, 2021). "Furthermore, both integrins (ITGA6 and ITGB1) were knocked down at the same time to examine the tumor suppressor effects, e.g., cell proliferation and migration, and invasive abilities." (PMID 34199886, 2021). "In conclusion, we showed that type I collagen could mediate the tumor progression and chemotherapy though an ITGB1 based manner, which was dependent on BCL9L/β-catenin/BCL2 signaling pathway." (PMID 34319913, 2021). "To confirm our hypothesis, we isolated those tumor tissues and examined the expression of ITGB1 and NF-κB." (PMID 34758833, 2021). "Additionally, IHC staining further confirmed that HCC tumor tissues displayed remarkably upregulated ITGB1 protein levels." (PMID 34977001, 2021). "As for ITGB1, elevated expression of ITGB1 was found in CR tumor tissues compared to CS group." (PMID 34319913, 2021). "Next, we evaluated the expression of ITGB1 in the tumor specimens of HCC patients." (PMID 34977001, 2021). "Furthermore, Itgb1 is found on MDSCs and bone marrow-derived immune cells which promote tumor inflammation." (PMID 34482371, 2021). "Intriguingly, PTX exhibited limited tumor suppressive effects in 3D collagen cultured SGC-7901 bearing mice, which might have been caused by drug resistance induced by collagen/ITGB1 signaling." (PMID 34758833, 2021). "Meanwhile, the tumor progression induced by ITGB1 was dependent on the presence of type I collagen." (PMID 34319913, 2021). "Expression of ITGA3 and ITGB1 was directly regulated by tumor-suppressive miR-124-3p." (PMID 34199886, 2021). "Given the strongly positive ITGB1 expression detected in HCC tumor, we next explored whether accumulated ITGB1 influence the overall survival of HCC patients by dividing the HCC cohort (n = 367) into high- and low-expression groups." (PMID 34977001, 2021). "Furthermore, bioinformatics analysis revealed that paxillin (PXN) and 14-3-3 protein zeta (YWHAZ) are the molecules participating in ITGB1-regulated HCC tumor cell cycle progression." (PMID 34977001, 2021). "Consequently, ITGB1 activity has been shown to be dominant to confer CAM-DR to tumor cells of different origin upon binding to COL1." (PMID 32668815, 2020). "Notably, ITGA3 and ITGB1 expression was directly regulated by tumor-suppressive miR-124-3p in PDAC cells." (PMID 32977589, 2020).